SETD2 (SET domain containing 2, histone lysine methyltransferase)
Diseases named in the same sentence as SETD2 in open-access papers (continued):
Sharing a sentence is not in itself a finding about the gene and the disease.
tumor (continued). "Secondly, due to the scarcity of primary tumor cells, we were not able to further study the SETD2 gene on epigenetic regulation of RNA processing." (PMID 32849799, 2020). "A prospective study examining frozen tissue qRT-PCR of AQP1, DDX11, BAIAP2L1, and six previously identified genes (PBRM1, BAP1, SETD2, KDM5C, FOXC2, and CLIP4) showed that expression of DDX11 was a significant factor for predicting tumor aggressiveness based on Fuhrman grade." (PMID 31963294, 2020). "Similarly, our results indicated that SETD2, SETD5, and SETMAR were frequently deleted in ccRCC and they were located at 3p, implying their potential roles as tumor suppressors." (PMID 30755832, 2019). "In tumor K448, we observed 5 distinct BAP1 mutations and 3 SETD2 mutations, but BAP1 and SETD2 mutations never co-occurred within the same clone." (PMID 29656894, 2018). "It is important to note that the initial tumor resections of three of these tumors were not sequenced for SETD2, so it is uncertain if the changes were present at the time of initial presentation." (PMID 30419952, 2018). "Of note, this patient’s tumor also possessed likely deleterious alterations in PAX5 and SETD2." (PMID 27974047, 2016). "HOTAIR overexpression promoted and HOTAIR knockdown inhibited the xenograft tumor formation, while HOTAIR overexpression plus SETD2 overexpression did not altered the xenograft tumor growth respectively." (PMID 26172293, 2015). "One cancer, P17, had acquired two small regions of deletion, one around SETD2 and the other around BAP1, although we did not detect pathogenic SNVs of either gene in this tumour." (PMID 25790038, 2015). "In contrast, AZD1775 treatment of tumors generated from SETD2-proficient U2OS cells did not have any significant effect on tumor growth (tumor size at day 12 = 257.5 ± 19.3 mm3 versus 292.5 ± 34.3 mm3, p = 0.37)." (PMID 26602815, 2015). "Interestingly, si-SETD2 alone did not affect tumor cell activity, but it increased ROS and Fe2+ levels (2C-2F)." (PMID 37604811, 2023). "While on the one hand this could be discordance, it could also be because we did not sequence the SETD2 gene in all tumor regions as this was not our main focus." (PMID 37120552, 2023). "Knockdown of SETD2 alone did not significantly alter tumor cell activity." (PMID 37604811, 2023). "Next, we compared the gene expression of SETD2-positive and negative tumor cells." (PMID 36035179, 2022). "SETD2 also methylates non-histone substrates such as α-tubulin which may promote genome stability and contribute to the tumor-suppressor function of SETD2." (PMID 35661267, 2022). "Molecular alterations in RCC tumors have been extensively studied in the last decade, especially in ccRCC but neither identified mutations (e.g.,: VHL, BAP1, PBRM1, SETD2, KDM5C, MTOR) nor transcriptome-based ccRCC tumor sub-classification have straightforward clinical relevance." (PMID 33535553, 2021). "In addition, in four of the 23 tumor types, alterations in PTEN, SETD2 and KRAS were identified." (PMID 35251119, 2021). "In the absence of Setd2, tumor progression has shown a rapid increase to almost 50%." (PMID 34781949, 2021). "However, MEITL typically presents as a tumor mass, harbors clonal TR gene rearrangements, and recurrent SETD2 alterations, not found in NKCE." (PMID 32696224, 2021).
tumor (continued). "Our findings suggested that SETD2 inhibited tumor growth via suppressing CXCL1-mediated activation of cell cycle, indicating that the regulation of H3K36me3 level by targeting SETD2 and/or the administration of downstream CXCL1 might represent a potential therapeutic way for new treatment in LUAD." (PMID 33223508, 2020). "Since ISGF3 is activated by HIF and suppressed after the loss of PBRM1, KDM5C, SETD2 or BAP1, it may function as the executioner of a negative feedback loop that potently opposes tumor growth." (PMID 30355451, 2018). "Interestingly, unlike SMYD2, another H3K36-specific methyltransferase SETD2 act as a tumor suppressor in lung cancer." (PMID 30002791, 2018). "Since the suppression of PBRM1, KDM5C, SETD2 or BAP1 all lead to the reduction of ISGF3, a potent tumor suppressor, it is possible that any effective therapeutic intervention that restores ISGF3 function could benefit ccRCC patients with a wide variety of mutations." (PMID 30355451, 2018). "Tumor size, cell type (clear/granular), Fuhrman’s grade, Staging, as well as immunostaining with Snail, ZEB1, Twist, Vimentin, E-cadherin, β-catenin, PTEN, p-Akt, p110α, and SETD2, were analyzed for intratumor heterogeneity using a classification and regression tree algorithm." (PMID 26951092, 2016). "Although tumours with either mutation in SETD2 or VHL, and both WT status did not change in size following TGX221 treatment, ACHN tumours were in general slightly larger than Caki-1 or 786O tumours." (PMID 25853938, 2015). "Therefore, we performed a Kaplan–Meier plots to investigate the clinical features between SETD2 SET domain mutation group and non-SET domain mutation group; results indicated that SETD2 SET domain mutation group was featured with advanced tumor stage and poor prognosis in ccRCC." (PMID 30755832, 2019). "Similar to SETD2 knockdown, FECH knockdown did not have a significant effect on cell activity, however, siFECH can increase the sensitivity of erastin to tumor cells." (PMID 37604811, 2023). "For example, global methylation variability, Euclidian distances between tumor regions and normal kidney, and overall CNV number were higher in sequence-based SETD2 wild-type tumors, but higher in IHC-based H3K36me3 negative tumor regions." (PMID 37120552, 2023). "Xenograft assays showed that SETD2 overexpression dramatically reduced tumor growth compared with the control group, while CXCL1 overexpression reversed tumor volume and weight regardless of the SETD2 expression level." (PMID 33223508, 2020). "In vivo, treatment of SETD2 mutant A498 cells, but not SETD2 proficient 786-0 cells, with AZD8186 significantly decreased tumor growth." (PMID 30774762, 2019). "When the SETD2 expression is reduced, it fails to effectively inhibit the expression of mesenchymal-related genes, leading to EMT in prostate cancer cells and thereby promoting tumor metastasis." (PMID 40959108, 2025). "While tumor cell lines are not ideal for studying EMT, we nonetheless examined whether SETD2 inactivation would further shift cancer cells along the epithelial –mesenchymal spectrum." (PMID 37418588, 2024). "For VHL wild-type tumors, other therapy modalities aiming at pVHL non-related pathways controlled by tumor suppressors such as PBRM1, SETD2 or BAP1 may be more appropriate than the common anti-angiogenic treatment." (PMID 27530247, 2016). "The absence of SETD2 in prostate cancer (PCa) cells promotes excessive activation of enhancer-binding protein 2 (EZH2), leading to an increase in whole genome H3K27me3 and chromatin repression, which in turn inhibits expression of tumor suppressor genes and promotes metastasis." (PMID 40786181, 2025). "Interestingly, none of VHL, SETD2, PBRM1 and BAP1 is indicated in these marker gene lists suspecting a missing link between the well-known DNA tumour markers and the actual behaviour of tumour cells." (PMID 35586183, 2022).
cancer (229 papers, 2011 to 2026). A tumor composed of atypical neoplastic, often pleomorphic cells that invade other tissues. "Our study provides the first mechanistic and three-dimensional protein structure information on how SETD2-associated cancer mutations can lead to altered H3K36 methyltransferase activity." (PMID 41654133, 2026). "Genetic inactivation of SETD2 during oncogenesis drives loss of H3K36me3, genomic instability, and cancer progression." (PMID 41827754, 2026). "Despite the clinical relevance of SETD2 missense mutations in cancer, their biochemical and structural consequences remain insufficiently characterized." (PMID 41654133, 2026). "SETD2 mutations are frequently observed in various cancers and tend to cluster within its catalytic SET domain." (PMID 41654133, 2026). "SETD2 is frequently mutated in multiple cancer types and encodes the histone 3 lysine 36 (H3K36) trimethyltransferase." (PMID 41228333, 2025). "Functionally, we show that SETD2 inhibition or cancer-associated SETD2 mutations render cells iron deficient, thereby driving resistance to ferroptosis and potentially explaining how some tumors evade antitumoral immunity." (PMID 40961184, 2025). "We also show that SETD2 mutations, which occur frequently in renal cell carcinomas, render these cancer cells resistant to ferroptosis, thereby uncovering a pro-oncogenic mechanism dependent on intracellular iron regulation." (PMID 40961184, 2025). "We identified all SETD2-mutated cancer and identified 500 consecutive cases prior to 4 January 2020 as a control group." (PMID 41228333, 2025). "One study indicates that SETD2 loss in cancer cell can shape cancer-associated fibroblasts heterogeneity to support cancer progression." (PMID 40959108, 2025). "Because of its role in proliferation, migration, and invasion, SETD2 is routinely associated with cancer." (PMID 39591760, 2025). "SETD2 is associated with various cancers and is considered as one of the most frequently mutated genes in tumors." (PMID 39591760, 2025). "Clinically in ccRCC, biallelic SETD2 alterations have been associated with adverse cancer-specific outcomes such as higher tumor stage, increased likelihood for recurrence or metastatic disease, and worse cancer-specific survival." (PMID 38920407, 2024). "In our first investigation, we explored the functional impact of SETD2 loss and its association with DNA methylation changes across diverse cancer types." (PMID 38253545, 2024). "These would be valuable to reveal underlying mechanisms by which mutations in BAP1 and SETD2 exert diverse effects on cancer progression in ccRCC." (PMID 38808948, 2024). "Overall, therapeutic targets for patients with SETD2-mutated cancers are still an unmet clinical need warranting further investigation." (PMID 38920407, 2024). "As a chromatin remodeling gene, SETD2 mutation was found to be associated with IO therapeutic response in a pan-cancer study." (PMID 38172737, 2024). "Prior preclinical studies demonstrated a significant synthetic lethal effect with single-agent WEE1 inhibition in SETD2-deficient cancer models including ccRCC." (PMID 38920407, 2024). "This is also the first study to show the association between SETD2-dependent methylation dysregulation and gene expression in cancer, as well as its link to the tumorigenic process (discussed in more detail below)." (PMID 37528416, 2023). "Clinical data analysis of cancer patients treated with immune checkpoint inhibitors demonstrated that SETD2 mutation is a potential biomarker." (PMID 37025591, 2023).
cancer (continued). "CcRCC is unusual for its high frequency of epigenetic regulator mutations, such as the SETD2 histone H3 lysine 36 trimethylase (H3K36me3), and low frequency of traditional cancer driver mutations." (PMID 37120552, 2023). "Here, we perform a pan-cancer analysis and show that both SETD2 mutation and reduced expression are associated with DNA methylation dysregulation across 21 out of the 24 cancer types tested." (PMID 37528416, 2023). "Loss of SETD2 and DNA methylation changes can both be early events in cancers, thus we wished to explore the role of SETD2 loss on DNA methylation dysregulation and tumorigenesis, which has not been studied before." (PMID 37528416, 2023). "In summary, SETD2, as a new tumor suppressor factor, exhibits gene mutation or low protein expression in many human malignant tumors, although the exact mechanism is unclear." (PMID 37359376, 2023). "Consistent with the requirement of histone chaperones for the establishment of an epigenetic landscape permissive for tumorigenesis upon SETD2 loss, SETD2-deficient cancer cells were more sensitive to genetic and chemical inhibition of histone chaperones." (PMID 36810256, 2023). "Loss of SETD2 in ccRCC is related to decreased autophagy processing, greater levels of general metabolic activity, poorer cancer-specific survival in ccRCC patients, and slower replication fork speed." (PMID 37025591, 2023). "To examine the occurrence of SETD2 mutations in different cancers, we first evaluated the SETD2 mutational prevalence." (PMID 37479966, 2023). "SETD2 deficiency is associated with cancer occurrence and progression by regulating autophagy flux, general metabolic activity, and replication fork speed." (PMID 37025591, 2023). "In this study, we conducted a pan-cancer analysis to disentangle DNA methylation changes associated with SETD2 variants in cancer." (PMID 37528416, 2023). "SETD2 loss sensitizes cancer cells to the inhibition of histone chaperones, FACT complex, or transcriptional elongation." (PMID 36810256, 2023). "In the TCGA cohort, SETD2 mutations were correlated with poorer cancer-specific survival in ccRCC patients." (PMID 37025591, 2023). "A 6726 Chinese pan-cancer population with 375 patients who had SETD2 mutations was retrospectively analyzed." (PMID 37479966, 2023). "This helps explain why SETD2 mutations occur in a wide variety of human cancers and are associated with diverse oncogenic drivers." (PMID 36810256, 2023). "We, thus, expanded the study to include more cancer types including those that show infrequent SETD2 mutations to explore if SETD2 downregulation also impacted on DNA methylation." (PMID 37528416, 2023). "Our study showed that a characteristic gene body hypomethylation phenotype is also present in both SETD2 mutated and low SETD2 expressing samples and is seen across multiple cancer types." (PMID 37528416, 2023). "Multiple SETD2-regulated cellular pathways suppress cancer development and uncover mechanisms underlying aberrant cell cycle regulation in SETD2-depleted cells." (PMID 37025591, 2023). "To study the effect of loss or depletion of H3K36me3 in cancer types that had a SETD2 mutation frequency of less than 3%, we used SETD2 expression data to group samples into high and low SETD2 groups." (PMID 37528416, 2023). "The TCGA pan-cancer cohort shows that patients with SETD2 mutations have a higher immune-related gene expression and MSI." (PMID 37025591, 2023). "Given SETD2’s large size, very few cancer mutations have been functionally studied for their effect on enzymatic activity, DNA binding, subcellular localization, or protein stability." (PMID 37120552, 2023). "Our findings thus provide new insights into the functional impact of SETD2 loss in cancer and suggest a new role for SETD2 in tumorigenesis and cancer aggressiveness through DNA methylation dysregulation." (PMID 37528416, 2023).
cancer (continued). "SETD2 is widely mutated across cancer types and affects H3K36 histone methylation most directly, but SETD2-mediated changes in H3K36 methylation have been linked to dysregulation of diverse cellular processes including DNA methylation and RNA splicing." (PMID 35761387, 2022). "Mutations in PTPRD, CREBBP, BRAF, NOTCH3, TERT, and SETD2, which are involved in various aspects of immune regulation, were reported as potential biomarkers in cancer patients after immunotherapy with improved survival." (PMID 36092890, 2022). "The first cancer-associated SETD2 mutations were described in ccRCC and much of the subsequent studies have focused on the role of SETD2 mutations in ccRCC." (PMID 35661267, 2022). "Noteworthily, we find that IDH1 and SETD2 mutations are potential shared drivers across nine CIMP-positive cancer types, albeit in sometimes rare subpopulations (such as in LUAD)." (PMID 35134107, 2022). "Among them, ARID1A, TSC2, JAK3, CIC, CINNB1, and SETD2 were mutated at the early stage of carcinogenesis, which played an essential role in advancing early cancer development and progression." (PMID 35795211, 2022). "Of note, in a preclinical study in SETD2-deficient cancers, WEE1 inhibition with adavosertib was shown to have antitumor activity in vitro and in vivo." (PMID 36230766, 2022). "A phase II trial investigating adavosertib in SETD-2 deficient cancers, including a cohort for advanced ccRCC, is ongoing (NCT03284385)." (PMID 36230766, 2022). "To summarize, mutations in H3.3 genes and SETD2 are found in distinct cancer types and both affect SETD2 activity but can do so in distinct manners." (PMID 35661267, 2022). "SETD2 is frequently mutated in cancers such as CCRCC (Clear Cell Renal Cell Carcinoma), and its deletion is embryonically lethal." (PMID 36035998, 2022). "Alterations such as focal deletions or missense variants in SETD2 have been described in several cancers." (PMID 34503197, 2021). "In another study, many cancer-associated genes exhibited alternative splicing variations in SETD2 deficient mouse intestines, such as Sirt7, Cdk4, Cdk7, Rab1a, and Lkb1." (PMID 34715919, 2021). "Cancer cells with SETD2 deficiency or mutations are more sensitive to WEE1 inhibitor Adavosertib, AKT-specific inhibitor, and PI3Kβ-specific inhibitors." (PMID 34715919, 2021). "Here, we investigated the characteristics of SETD2 somatic mutation in the cancer genome atlas pan-cancer cohort." (PMID 34127768, 2021). "Further examination of cancer patients treated with immune checkpoint inhibitors suggested SETD2 mutation was associated with favorable clinical outcomes." (PMID 34127768, 2021). "We first examined the prevalence of SETD2 somatic mutations in the cancer genome atlas (TCGA) pan-cancer cohort." (PMID 34127768, 2021). "We already tested that one such mutation in cancer I214V, a substitution also found in hnRNP LL, results in weaker binding of SETD2." (PMID 34750379, 2021). "Changes in the expression of both SETD2 and hnRNP L are known to be associated with cancer progression." (PMID 34750379, 2021). "De facto, the prevalence of SETD2-inactivating mutations in cancer has the highest frequency in ccRCC8." (PMID 31988284, 2020). "The mutation of SETD2 gene in ccRCC has a proportion of 34.07%, with such a mutation being related to producing an aggressive cancer phenotype 63." (PMID 32231741, 2020). "SETD2 has been implicated in a number of cellular processes, many of which are dysregulated in cancer." (PMID 30818762, 2019). "The strongest predictor of high ITH in both KIRC alone or across several cancer types was the presence of mutations in SETD2, DNMT1 and DNTM3A." (PMID 30897760, 2019). "Our pan-cancer analyses revealed that mutations in epigenetic modifiers, namely SETD2 and DNMT3A, are major determinants of ITH." (PMID 30897760, 2019).